CD34 (CD34 molecule)
Diseases named in the same sentence as CD34 in open-access papers (continued):
Sharing a sentence is not in itself a finding about the gene and the disease.
neutropenia (26 papers, 2003 to 2025). A decrease in the number of neutrophils found in the blood. "Neutropenia in copper deficiency may result from decreased neutrophil survival or inhibited differentiation of CD34(+) hematopoietic progenitor cells." (PMID 39268301, 2024). "However, these are occasionally associated with failure to collect adequate doses of CD34+ stem cells or significant toxicities, including infectious complications due to prolonged neutropenia." (PMID 37835477, 2023). "Complications include poor graft function necessitating a CD34+ cell boost to support engraftment, as seen in our patient, who developed severe neutropenia and remained platelet transfusion dependent." (PMID 41245943, 2025). "G-CSF is used clinically to reduce chemotherapy-induced neutropenia and to treat severe chronic neutropenic disease as well in healthy donors to induce mobilization of CD34+ progenitor cells for transplantation." (PMID 33800710, 2021). "This is an important issue, since G-CSF is used not only to treat different types of CN, but is also applied for chemotherapy-induced neutropenia and to induce mobilization of CD34+ stem and progenitor cells for autologous or allogeneic transplantation." (PMID 30891028, 2019). "In the group aged < 24 months, we observed a significant correlation between the persistence of neutropenia and decreased circulating CD34+ cells (Pearson χ2 p = 0.008)." (PMID 30870474, 2019). "In view of these concerns, several strategies have been explored to enhance engraftment and shorten neutropenia, such as the infusion of double-cord blood units, CD34+ cells ex-vivo expansion or co-infusion of CD34+ cells from a third-party donor." (PMID 27872731, 2016). "The length of neutropenia, the delayed lymphocyte recovery, the low cell dose content of the graft, such as total nucleated cells, CD34+ and CD8+ cells are frequently observed in this scenario." (PMID 27872731, 2016). "To date, the only procedure that has demonstrated to shorten neutropenia is so called “haplo-cord” transplants in which CD34+ selected cells from the mobilized peripheral blood of an HLA-mismatched third-party donor are co-infused with the UCB unit." (PMID 27872731, 2016). "The tumor-primed NK cells he received were manufactured from a second, HLA-mismatched brother and, in response to his post treatment neutropenia, he received a CD34 selected top-up graft from his original matched sibling donor." (PMID 26062124, 2015). "The duration of neutropenia, duration of severe neutropenia and duration of hospitalization was significantly superior in patients receiving less than 5.0 × 106 CD34+ cells/kg." (PMID 24096822, 2014). "We noted similar median numbers of CD34 cells infused and numbers of red blood cell and platelet transfusions in both groups, except for the duration of neutropenia." (PMID 24089671, 2013). "Recent use of haemopoietic growth factors has allowed the reduction of neutropenia and has given the possibility of mobilising and harvesting an adequate number of haemopoietic CD34+ stem cells." (PMID 12569382, 2003). "SBDS co-localizes with the mitotic spindle, suggesting a role for SBDS in the cell division process, which corresponds to the decreased proliferation capacity of SDS-patient bone marrow CD34+ hematopoietic progenitor cells in our culture system and also to the neutropenia in SDS patients." (PMID 19759903, 2009). "Identification of mobilised PBSC by CD34+ expression and collection by leukapheresis has demonstrated that the period of neutropenia and thrombocytopenia may be shortened by increasing the dose of CD34+ cells transplanted." (PMID 17971220, 2007). "However there still remains a period of clinically significant neutropenia and thrombocytopenia which cannot be reduced by increasing CD34+ cell doses." (PMID 17971220, 2007).
neutropenia (continued). "Our findings may have a potential clinical impact: reduced CFU-GM levels were significantly correlated with the duration of neutropenia and moderate-severe infections requiring hospitalization were more frequent in patients with decreased circulating CD34+ cells and increased apoptotic rates." (PMID 30870474, 2019). "Interestingly, duration of neutropenia (9 vs 8 days, P=0.046), duration of severe neutropenia (7 vs 6 days, P=0.014) and duration of hospitalization (19 vs 18 days, P=0.028) were superior in patients receiving less than 5.0=106 CD-34 cells/kg." (PMID 24096822, 2014). "Taken together, addition of serum which was taken during neutropenia significantly enhances proliferation of HPC and maintains expression of CD34 for more cell divisions." (PMID 21437259, 2011). "We observed a trend, though not significant, towards the persistence of neutropenia in patients with decreased circulating CD34+ cells (Pearson χ2 p = 0.07)." (PMID 30870474, 2019). "Firstly, the faster recovery from neutropenia and reduced time for platelet transfusion dependency observed in the MPB-GT group is in line with HSCT results, and it importantly suggests that the in vitro manipulation per se does not introduce changes in the overall characteristics of CD34+ cells." (PMID 37244942, 2023).
ovarian carcinoma (26 papers, 2006 to 2025). A malignant neoplasm originating from the surface ovarian epithelium. "In this study, we primarily used CD34+ HPC-derived NK cells that have already been shown to be able to efficiently kill ovarian cancer cells in vitro and in vivo, and these cells are currently tested in a phase I study in EOC patients (NCT03539406)." (PMID 39376560, 2024). "We establish disseminated ovarian cancer PDX models in humanized NBSGW (huNBSGW) mice engrafted with human cord blood–derived CD34+ HSCs." (PMID 36860657, 2023). "For example, CD34-positive lineage ovarian cancer stem-like cells sorted using the side population procedure were injected into the mammary fat pads of BALB/c nu/nu mice." (PMID 35723396, 2022). "The results of studies that evaluated the association between MVD of other biomarkers, including CD34, CD31, and CD105, and epithelial ovarian cancer prognosis, were controversial." (PMID 35463733, 2022). "To determine the effect of HATMSC2 -MVs on the phenotype of ovarian cancer cell lines treated at the ratios of 10:1 and 100:1, we tested the presence of the CD34, CD44, CD133, SSEA4, CD73, CD90, and CD105 markers using flow cytometry." (PMID 33266317, 2020). "Preliminary evidence suggests presence of CD34+ (marker for CECs) cells in the blood of ovarian cancer patients." (PMID 31319587, 2019). "The microvessel density (MVD) of ovarian carcinoma was determined by immunohistochemistry with anti-CD34 as the label." (PMID 23426648, 2013). "To determine the correlation between AT1R expression and tumour angiogenesis, we assessed the intratumour MVD by counting CD34-positive microvessels in the same series of ovarian cancer tissues (n=67)." (PMID 16434990, 2006). "These organoids recapitulate High‐Grade Serous Ovarian Cancer organoids' histological and molecular heterogeneity while preserving the critical immune microenvironment and blood vessels, as evidenced by the presence of CD34+ endothelial cells." (PMID 39206413, 2024). "NK cells derived from human CD34+ hematopoietic stem and progenitor cells showed efficient infiltration and killing of human ovarian cancer spheroids using an in vivo-like model system and reduced tumor progression in mice xenografted with ovarian carcinoma." (PMID 30805309, 2019). "In addition, tumor xenografts derived from Oct4A KD cells displayed relatively lower abundance of markers associated with ovarian cancer (CK7), cancer metabolism (Glut-1) and angiogenesis (CD31 and CD34)." (PMID 27390927, 2016). "To determine whether VM could be discovered in tissues obtained from 90 ovarian cancer patients, we identified the endothelium and VM channel in ovarian cancer tissues using anti-CD34 and periodic acid-Schiff (PAS), respectively." (PMID 26992227, 2016). "The animal experiment results indicated that transferring CD34+ UCBSC- IL-21 into A2780 ovarian cancer xenograft-bearing nude mice augmented the therapeutic effect on ovarian cancer, however, IL-21 expression was gradually decreased in the mouse tumor sites 21 days posttransplantation." (PMID 24444073, 2014). "We did not observe upregulation of prototypical endothelial cell markers (CD31, CD34, VE-cadherin, Icam1, and Vcam1) upon ectopic expression of FOXC2 in mouse ovarian cancer cells." (PMID 36230774, 2022). "A separate hierarchical cluster of immature or stem-like cell populations (n = 4) was identified, which expressed CD133, CD34, or both, as well as CD24, a marker found on both immature leukocytes and ovarian cancer cells." (PMID 33670410, 2021). "In our previous studies in vivo, we showed a significant increase in CSCs: CD24, CD34, CD44, CD117, ALDH1 and OCT4, in tumors collected from animals bearing orthotopic ovarian cancer followed by treatment with cisplatin." (PMID 29190952, 2017). "In ovarian cancer, the most common CSCs identified include CD24, CD34, CD44, CD117, ALDH1, EpCAM, SSEA4, NANOG, MYD88, and SOX2 positive cells." (PMID 29190952, 2017).
ovarian carcinoma (continued). "We next attempted to characterize EPCs-specific markers CD34 and VEGFR2 in the peripheral blood of patients with ovarian cancer by real-time RT-PCR." (PMID 20334653, 2010). "Immunohistochemical staining for AT1R, VEGF, CD34 and proliferating cell nuclear antigen (PCNA) were analysed in ovarian cancer tissues (n=67)." (PMID 16434990, 2006). "In the ovarian cancer tissues, further significant positive correlations were observed between DAB2 and CSC markers (CD34, ALDH1A1, CD117 (Kit)) and mesenchymal markers (MMP9, SNAI1 and MMP3) and negative correlations with mesenchymal markers (CDH2, FOXC2 and SOX10)." (PMID 37815603, 2023). "Pretreatment CD34 mRNA levels were not significantly increased in ovarian cancer patients compared with healthy controls; however, VEGFR2 expression was increased, and plasma levels of VEGF and MMP-9 were also elevated." (PMID 20334653, 2010). "In addition, we used real-time quantitative reverse transcription polymerase chain reaction (RT-PCR) to evaluate mRNA levels of EPC-specific markers CD34 and vascular endothelial growth factor receptor 2 (VEGFR2) in the peripheral blood of ovarian cancer patients." (PMID 20334653, 2010). "Interestingly, pre-treatment VEGFR2 mRNA expression was increased in ovarian cancer patients compared with healthy controls, but no significant alteration was observed in CD34 mRNA levels." (PMID 20334653, 2010). "Levels of CD34 were not significantly different in pre-treatment ovarian cancer patients compared with healthy controls, whereas VEGFR2 expression in pre-treatment ovarian cancer patients was 61-fold higher compared with healthy controls (P = 0.013)." (PMID 20334653, 2010).
viral infection (26 papers, 2006 to 2024). "We have now established that HIV-1-infected human host CD4+ thymocytes secrete and differentially regulate the host miRNA factors, miR-15a and miR-24, to cause inhibition of differentiation of these virus infection-resistant CD34+ cells in an indirect manner." (PMID 38721526, 2024). "The conventional method of graft size determination based on CD34+ cells with alemtuzumab serotherapy is associated with delayed immune reconstitution, contributing to an increased risk of viral infections and graft failure." (PMID 38200046, 2024). "NSG mice transplanted with human CD34+ HSC have been previously shown to mount human-like immune responses to viral infections, including those caused by HIV, Ebola virus, dengue virus, and adenovirus, among others." (PMID 31550241, 2019). "Human cytomegalovirus (HCMV) can establish latency following infection of CD34+ hematopoietic progenitor cells (HPCs), and reactivation from latency is a significant cause of viral disease and accelerated graft failure in bone marrow and solid-organ transplant patients." (PMID 31431555, 2019). "involvement of exosomes) between the HIV-infected CD4+ thymocytes and this virus infection-resistant CD34+ HSPCs through miRNA transfer from the CD4+ to CD34+ cells requires continued investigation." (PMID 38721526, 2024). "Here we report a dataset that captures changes in the miRNAome of virally infected CD34+ cells during the initial stages of viral infection." (PMID 37080390, 2023). "Here, we identify 72 significantly upregulated miRNAs and three that were downregulated by 6hpi of infection of CD34+ cells which were then subject to multiple in silico analyses to identify potential genes and pathways important for viral infection." (PMID 37080390, 2023). "Viral infections were found more frequently in the CD34-selected group than in the unmanipulated group (CD34-selected, 9/11 patients; unmanipulated, 2/8 patients; p = 0.02)." (PMID 30670057, 2019). "To this end, we examined the tissue sites for viral infection in bone marrow, blood, spleens, liver, gut, brain, kidney and lungs of human CD34+ hematopoietic stem cell engrafted virus-infected NOD.Cg-PrkdcscidIl2rgtm1Wjl/SzJ mice." (PMID 26996968, 2016). "GFP was expressed in Nile red-positive adipocytes and stromal cells expressing CD34+ or Sca-1+ 48 hr after viral infection." (PMID 22292082, 2012). "Here we evaluated the capacity of hES cell derived CD34 cells to give rise to normal macrophages as a first step towards using these cells in viral infection studies and in developing novel stem cell based gene therapy strategies for AIDS." (PMID 16623949, 2006). "Here, we propose that the seed, soil, and insect theories of aplastic anemia also apply to PGF; CD34+ cells are compared to seeds; the bone marrow microenvironment to soil; and virus infection, iron overload, and donor-specific anti-human leukocyte antigen antibodies to insects." (PMID 35720412, 2022). "Previous studies of the effect of viral infection on megakaryocytes derived from CD34+ cells showed that human immunodeficiency virus (HIV), human herpesvirus 6 and human cytomegalovirus negatively affected the survival, differentiation and/or maturation of megakaryocyte progenitors." (PMID 20419155, 2010). "Despite having detectable anti-viral T cells, CD34+-humanized and BLT mice generally exhibit weak humoral responses after viral infection." (PMID 33692812, 2021). "To study disease patterns seen after viral infection and immune suppression, we constructed NOD.Cg-PrkdcscidIl2rgtm1Wjl/SzJ (NSG) mice reconstituted with CD34+ human stem cells (HSC)." (PMID 28279181, 2017). "Despite generation of a primary immune response in CD34+T-NSG mice, the antibody responses are quite weak and largely restricted to immunoglobulin M (IgM) due to inefficient class switching, specifically after virus infection." (PMID 32457941, 2020).
viral infection (continued). "CD34 mice are completely relevant for investigation of infected T cell, macrophage and progenitor stem cells operative during HIV infection and reflect the dynamics of viral infection that occurs in a human host." (PMID 26996968, 2016). "Our results show that blocking or down-regulating TfR1 surface expression in CD34+ cells significantly reduced both JUNV replication as well as the decrease in platelet formation induced by JUNV infection, indicating that viral infection is a necessary event for the inhibition of platelet formation." (PMID 20419155, 2010). "As surface expression of EGFR is not well established in CD34+ HPCs, we first investigated EGFR surface levels in the context of WT, UL135STOP and UL138STOP virus infection using EGF-647." (PMID 27218650, 2016).
heart failure (25 papers, 2010 to 2025). Inability of the heart to pump blood at an adequate rate to meet tissue metabolic requirements. "In order to delineate the constitution map of human cardiac resident CD34 lineage cells during heart failure, we extracted the cells that expressing CD34 from the human single-cell RNA sequencing data, which were CD34+ cells." (PMID 36805782, 2023). "It is of great significance to scrutinize the fate and the mechanism of CD34+ cell differentiation in vivo during heart failure and explore its intervention strategy." (PMID 36805782, 2023). "In our study, by detailed analysis of tdTomato+ macrophage population, the percentage of resident macrophage in CD34+ cell lineage significantly increased in the progression of hypertrophy and heart failure." (PMID 36805782, 2023). "We then performed scRNA-seq in CD34 lineage between control- and heart failure-groups, total number of 9,457 cells were captured and passed the quantity control for further analysis." (PMID 36805782, 2023). "Taken together, patients with heart failure displayed a marked alterations of cell landscape in heart tissues implicating a contribution of CD34+ cells to fibrosis." (PMID 36805782, 2023). "Primary tdTomato + cells isolated from the heart of TAC-induced heart failure mice exhibited high heterogeneous both in cell size and cell morphology in comparison with CD34+ cells isolated from the TAC 0 control mice." (PMID 36805782, 2023). "Real-time PCR showed that cardiac CD34 mRNA level was decreased in TAC-induced heart failure mice, and then was further reduced in rAAV9-miR-665-treated TAC mice, while rAAV9-miR-665 TUD treatment showed the opposite effect." (PMID 30243022, 2018). "In the present study, we observed that miR-665 involved in the process of heart failure by reducing coronary microvessel angiogenesis via CD34." (PMID 30243022, 2018). "Consistently, CD34 expression was significantly decreased in human heart with heart failure as detected by immunohistochemical assays." (PMID 30243022, 2018). "We conclude by describing a case report of a heart failure patient treated with a combination stem cell protocol in an attempt to augment beneficial aspects of cord blood CD34 cells and mesenchymal-like stem cells." (PMID 20398245, 2010). "Moreover, in a mouse model of heart failure, the depletion of CD34+ cells resulted in a reduction in FABP4+ fibroblasts, triglyceride (TG) content, and myocardial fibrosis and an improvement in cardiac function." (PMID 39198543, 2024). "CD34+ cells have been used to treat the patients with heart failure, but the outcome is variable." (PMID 36805782, 2023). "The scientific literature reports that bone marrow is a rich source of CD34 + stem cells that could be used for myocardial repair to prevent heart failure in patients." (PMID 37574547, 2023). "Furthermore, depletion of CD34+ cells in the mouse model of heart failure leads to decreased myocardial fibrosis and improved cardiac function." (PMID 36805782, 2023). "Treatment of heart failure with CD34+ cells from bone marrow has been carried out for decades." (PMID 36805782, 2023). "Other cell types are still waiting the final verdict, but with the exception of the CD34+ cells (limited to angiogenesis) it is unlikely that any other marrow-derived cell type may bring real benefits to heart failure patients." (PMID 33912054, 2021). "However, the initial active player M_SH, co-expressing Ackr3, Cd34, Cd248, and Pi16, was reported as cardiac mesenchymal-like stem cells with multilineage differentiation and self-renewal capacities, and promoted heart failure." (PMID 37147443, 2023). "Moreover, a model was used to illustrate the roles of Sp1, miR-665 and CD34 in heart failure." (PMID 30243022, 2018). "Therefore, increased Sp1 in TAC-induced heart failure mice may lead to an increase of miR-665, then reduce CD34 level, finally aggravate heart failure." (PMID 30243022, 2018).